CDKN2A (cyclin dependent kinase inhibitor 2A)
Diseases named in the same sentence as CDKN2A in open-access papers (continued):
Sharing a sentence is not in itself a finding about the gene and the disease.
glioma (continued). "The CDKN2A homozygous deletion is a significant prognostic factor in IDH-mutant glioma patients across multiple histologic WHO grades." (PMID 34638714, 2021). "In contrast, gliomas from older patients were more likely to be IDH-WT with EGFR mutations, chromosome 7 gain and 10 loss, CDKN2A deletion and worse prognosis." (PMID 33879792, 2021). "The prognostic significance of EGFR and CDKN2A alterations on regulated genes in patients with glioma was determined using the TCGA and the Chinese Glioma Genome Atlas (CGGA) datasets." (PMID 33959491, 2021). "Many studies have reported that CDKN2A deletion is associated with significantly shorter PFS and OS in both lower-grade glioma (LGG) and HGG." (PMID 34638714, 2021). "Copy number mutations of CDKN2A and EGFR have been reported as early events in glioma development, whereas PTEN alterations have been described to occur later." (PMID 32604718, 2020). "Some of the most relevant mutations in gliomas are the homozygous and hemizygous deletion at Ch9p21, which involves the genetic loss of CDKN2A (p16INK4)." (PMID 32516884, 2020). "In conclusion, our data highlight the importance of a glioma patient stratification based on the CDKN2A-IFN gene cluster deletion." (PMID 32516884, 2020). "Loss-of-function mutations of CDKN2A and NF1 have been observed as drivers in a range of human gliomas including LGG and GBM." (PMID 32727536, 2020). "More recent studies have reported that homozygous loss of chromosome 9p21 with loss of CDKN2A, a common phenomenon in higher WHO grade gliomas, is also associated with a worse outcome in IDH-mutant astrocytomas and oligodendrogliomas." (PMID 32444979, 2020). "We have analyzed the CDKN2A-IFN I gene cluster in 1018 glioma tumors and evaluated the NDV oncolytic effect in six GBM CSCs ex vivo and in a mouse model." (PMID 32516884, 2020). "ccfDNAs in glioma were associated with differential methylation levels of MGMT, cyclin-dependent kinase inhibitor 2A, multiple tumor suppressor 1 p16/(INK4a), p73, and retinoic acid receptor beta (RARb)." (PMID 32849827, 2020). "Homozygous deletion of CDKN2A is also observed in pLGG, albeit at a lower frequency than in adult glioma." (PMID 32164789, 2020). "The existing literature on use of FISH specifically to detect CDKN2A homozygous deletion in gliomas is sparse." (PMID 33081848, 2020). "Of importance is that locus 9p22.1–p21.3 (p16INK4a/p14ARF/p15INK4b) has been known to encompass the CDKN2A gene frequently deleted in gliomas." (PMID 30871102, 2019). "To date, only concomitant deletion of the CDKN2A locus has been described to synergistically promote glioma development and to define inferior outcome in BRAFV600E-positive glioma." (PMID 31391125, 2019). "Deletion of Ink4a, an important tumor suppressor, produces the same effect as CDKN2A loss (which encodes p16INK4a) in gliomas." (PMID 31345255, 2019). "While homozygous deletion of CDKN2A is found in > 55% of adult high-grade glioma, it is rarely seen in pediatric high-grade glioma." (PMID 30101054, 2018).
glioma (continued). "The top three genes found in the Glioma signaling network, CCND1, CDKN2A, and RB1, are frequently overexpressed, mutated, and/or deleted in glioma]." (PMID 29912931, 2018). "When these experiments were undertaken in Cdkn2a-null mice, the gliomas formed with a shorter latency and were of higher grade." (PMID 29052807, 2017). "Retroviruses carrying v-sis (PDGFB) injected into normal mice have yielded astrocytic tumors, with varying glioma types generated when injected in Cdkn2a-null mice." (PMID 29052807, 2017). "Array CGH and exome sequencing of a population of matched pediatric low-grade glioma (PLGG) and secondary high-grade glioma (sHGG) identified BRAFV600E mutation and CDKN2A deletion as the most recurrent alterations in sHGG, at 39% and 57% respectively." (PMID 27713119, 2016). "Regions harboring EGFR (7p11.2) or CDKN2A (9p21.3) were the most frequently amplified or deleted region in the RMPAhigh gliomas." (PMID 27385209, 2016). "Mistry and colleagues described a series of pediatric secondary high-grade gliomas harboring BRAF mutation and CDKN2A deletion, showing longer latency to transformation from low-grade lesion and better clinical outcome." (PMID 26452024, 2016). "In the present study, we investigated and show the occurrence and correlations between alterations at CDKN2A/B, 1p/19q, IDH and the TERT promoter mutations in different histological sub-types of gliomas and their effect on patient survival." (PMID 25797251, 2015). "On the other hand, EGFR gain is significantly rarer overall in IDHmut gliomas (17 % grade II–III, 25 % grade IV) and CDKN2A loss is slightly lower (39 % grade II–III, 42 % grade IV) compared with IDHwt." (PMID 26091668, 2015). "A recent study using a glioma model in which there is concomitant BRAF V600E mutation and CDKN2A loss, as seen in our patient, demonstrated that these tumors respond to asingle-agent BRAF inhibitor." (PMID 25563358, 2014). "Our results indicated that suppressing the expression of CDKN2A was able to promote the low grade gliomas to high grade gliomas." (PMID 21843312, 2011). "Meanwhile, Transfection of CDKN2A into glioma cells resulted in a reduction in the rate of cell growth." (PMID 21843312, 2011). "CDKN2A is an important positive regulator of the cyclin-Rb signaling pathway involved in carcinogenesis of glioma." (PMID 21843312, 2011). "The result shows that the high grade glioma cells have a lower levels of CDKN2A than that of low-grade glioma cells, which in consistent with glioma tissues from patients." (PMID 21843312, 2011). "Here we show that a lower expression of CDKN2A and a higher expression of cyclin D1 in the patients with high-grade malignant gliomas than low-grade gliomas, respectively." (PMID 21843312, 2011). "To confirm the role of CDKN2A in gliomas, we detected the levels of CDKN2A expression in 61 glioma tissues by immunohistochemstry (IHC) and western blot." (PMID 21843312, 2011). "The results indicated that overexpression CDKN2A has the potential to be developed into a future treatment for glioma patients." (PMID 21843312, 2011). "Our results show that the expression levels of CDKN2A in high-grade glioma tissues were significant lower than that in low-grade glioma tissues." (PMID 21843312, 2011).
glioma (continued). "The Human Protein Atlas illustrated moderate or strong staining in 9 of 12 samples for TYMS and 5 out of 12 glioma samples for CDKN2A." (PMID 21365010, 2011). "Homocygote deletions of CDKN2A/B have been identified in both low-grade and high-grade gliomas." (PMID 41438586, 2026). "Alterations of CDKN2A/B have also been observed in the context of glioma." (PMID 41438586, 2026). "Germane to these genetic alterations, if harboring cyclin dependent kinase inhibitor 2A/B (CDKN2A/B) homozygous deletion, the impact on prognosis of the IDH mutated gliomas equals that of World Health Organization (WHO) grade 4 tumors rendering it of pivotal relevance." (PMID 39578301, 2025). "The functional correlation between CDKN2A/B homozygous deletion and invasive tumor behavior in gliomas may result from direct interference with IDH-regulated tumor biology." (PMID 41201287, 2025). "Notably, in IDH1/2-mutant glioma, CDKN2A/B deletion and EGFR amplifications were rare but confined to high-grade gliomas." (PMID 41377022, 2025). "By correlating ITSS with a comprehensive panel of molecular alterations (including IDH mutation, 1p/19q co-deletion, and CDKN2A/B homozygous deletion), our findings demonstrate the relevance of semiquantitative ITSS grading in the current era of molecularly driven glioma characterization." (PMID 40507765, 2025). "While there are limited data linking CDKN2A/B loss to chordomagenesis, studies in other solid tumors, such as glioma, have suggested that CDKN2A/B deletion may confer resistance to certain therapies." (PMID 41404256, 2025). "Homozygous deletions of CDKN2A, the gene that codes for P16, result in unregulated cell division through disinhibition of CDK4/6 and have been implicated in multiple cancer types, including in BRAF V600E gliomas." (PMID 40094009, 2025). "A meta-analysis including 714 patients demonstrated that the median overall survival of patients with IDH-wildtype gliomas harboring homozygous CDKN2A deletion was 13.0 months, compared with 18.0 months in patients without the deletion (p = 0.014, log-rank test)." (PMID 41567539, 2025). "However, the implications of CDKN2A/B deletion status regarding survival is complex in the novel stratification of gliomas by the IDH status." (PMID 39593128, 2024). "However, until now, only a few comprehensive studies have reported on the effect of CDKN2A/B homozygous deletion on the prognosis of CNS WHO grade 4 gliomas of the IDH wildtype." (PMID 39457569, 2024). "In other work, it was shown that copy number variation (CNV) was more frequent in recurrent tumors and CDKN2A/B loss was significantly enriched in the sample, but that study included IDH1/2 mutant glioma, where CDKN2A/B deletion is a marker of tumor progression." (PMID 39684714, 2024). "Eventually, these findings might provide information that aid future clinical studies investigating targeted drug therapies for IDH-mut/IDH-wt gliomas with CDKN2A/B gene alterations." (PMID 39593128, 2024). "Thus, the loss of key tumor-suppressor genes, especially CDKN2A/B, undermines IDH mutation’s suppressive effects concerning more aggressive glioma types." (PMID 39593128, 2024). "Moreover, NGS of glioma is now justified to look for CDKN2A/B homozygous deletions that upgrade IDH-mutant astrocytomas to grade IV, and EGFR amplification, chromosome (+ 7/-10) and TERT promoter mutations that upgrade IDHwt astrocytomas to grade IV." (PMID 39361075, 2024).
glioma (continued). "Imaging necrosis was significantly associated with glioma-related key gene mutations, such as 1p19q non-codeletion and CDKN2A/B homozygous deletion." (PMID 38378035, 2024). "CDKN2A/B homozygous deletion was found in one patient (2.3%) with IDH-mutant glioma." (PMID 37581661, 2024). "Earlier work reported worse survival for gliomas with heterozygous deletion of CDKN2A/B." (PMID 39382765, 2024). "In grades 2 and 3 gliomas, IDH mutations seemed to be related to lower HMGB2 expression; however, in grade 4 astrocytomas, HMGB2 expression was significantly higher in A4IDHmut, which bear CDKN2A/B homozygous deletions, compared to GBMs at IHC." (PMID 38672598, 2024). "CDKN2A/B deletions are prognostically relevant in low- and high-grade gliomas." (PMID 39593128, 2024). "Although both CDK4 amplifications and loss of CDKN2A/B have been largely described in gliomas, they do not seem to cooccur." (PMID 39211518, 2024). "Although many studies and reviews have shown that CDKN2A/B deletion is associated with poor prognosis in diffuse glioma with IDH1/2 mutation, relatively few have reported comprehensively on CNS WHO grade 4 gliomas." (PMID 39457569, 2024). "Therefore, the conclusions drawn from our study require further validation in prospective randomized clinical trials and meta-analysis including multiple studies on the prognostic role of CDKN2A/B deletion in CNS WHO grade 4 gliomas." (PMID 39457569, 2024). "We hypothesized that CDKN2A/B deletion may play a similar role in CNS WHO grade 4 gliomas because it is a factor that deteriorates the prognosis of diffuse glioma, especially with IDH mutation." (PMID 39457569, 2024). "CDKN2A deletion had been detected in gliomas, which could serve as a molecular biomarker for prognosis." (PMID 37570630, 2023). "CDKN2A homozygous deletion was recently shown to be associated with a poor prognosis close to that of glioblastomas for IDH-mutant gliomas lacking 1p/19q codeletion, as well as for OD3s." (PMID 37370678, 2023). "In pilocytic astrocytomas, CDKN2A inactivation also heralds more aggressive clinical behavior; its presence in astrocytomas with piloid features is now suggestive of a distinct high-grade glioma subtype." (PMID 37138345, 2023). "According to data analysis results, in four genetic models (AM, RM, DM and C-DM) TERT gene rs2736100 polymorphism, CCDC26 gene rs4295627 polymorphism, CDKN2A/B gene rs4977756 polymorphism and RTEL1 gene rs6010620 polymorphisms increased the risk of glioma in Caucasians to different degrees." (PMID 37746290, 2023). "Immunohistochemistry (IHC) has been used to identify CDKN2A HD in gliomas with mixed results." (PMID 37504251, 2023). "Furthermore, both pancreatic tumors and gliomas exhibiting CDKN2A LOF demonstrated a decreased cytolytic activity." (PMID 37936609, 2023). "Nevertheless, although CDKN2A homozygous deletion was rare in our cohort, with only one case of PA, its presence in cases of low-grade MAPK-induced gliomas showed a dramatic clinical evolution, pointing out the possibly strong prognostic impact of CDKN2A homozygous deletion in those populations." (PMID 36900302, 2023). "Finally, we combined the results of the XGB model and univariate Cox regression analysis to identify age, FGFR2, IDH1, CDK4, CDK6, KIT, and CDKN2A as crucial predictors of prognosis and OS time for glioma patients." (PMID 37273702, 2023). "In addition to IDH1/2 mutation, MGMT promotor methylation, EGFR amplification, TERT promotor mutation, and CDKN2A/B homozygous deletion, we sought to elucidate the alterations of other potential molecular biomarkers that might provide clues for clinical decision-making in gliomas." (PMID 36998447, 2023). "CDKN2A deletion has been associated with prognosis in other cancers, such as gliomas, but not in PCa." (PMID 37239316, 2023). "In low-grade gliomas, CDKN2A homozygous deletion seems to be an extremely rare event." (PMID 36900302, 2023).
glioma (continued). "Glioma development did not occur when mutant Idh1 was expressed in a genetic background with loss of Cdkn2a, Atrx, and Pten in vivo." (PMID 36765553, 2023). "Hence, CDKN2A/B homozygous deletion has been highlighted as a prognostic marker of astrocytoma mutants in the updated glioma classification for 2021." (PMID 37190513, 2023). "Furthermore, researchers have revealed the CDKN2A homozygous deletion is a prognostic molecular biomarker for IDH-mutant glioma patients." (PMID 37570630, 2023). "While CDKN2A homozygous deletion (HD) has been recognized as both a diagnostic and a prognostic marker in gliomas and meningiomas, its detection is not widely accessible and cost effective." (PMID 37138345, 2023). "Thus, this study aimed to develop a predictive model of CDKN2A/B in gliomas and investigate the prognostic value of this biomarker and radiomic features in isocitrate dehydrogenase (IDH)-mutant LGGs." (PMID 37190513, 2023). "The publication of the WHO 2021 classification saw the addition of CDKN2A or CDKN2B homozygous deletion as a new prognostic factor for IDH-mutated noncodeleted gliomas." (PMID 37370678, 2023). "In Asian populations, the CCDC26 gene rs4295627 polymorphism and CDKN2A/B gene rs4977756 polymorphism did not exhibit a relevance to the risk of glioma." (PMID 37746290, 2023). "However, the most pertinent of these latter studies was analysed by a meta-analysis assessing the association between CDKN2A HD and survival in IDH-mutant glioma." (PMID 37504251, 2023). "The cyclin-dependent kinase inhibitor 2A (CDKN2A) gene homozygous deletion has also been shown to be associated with dismal outcomes for IDH-mutant gliomas lacking 1p/19q codeletion, as well as for anaplastic ODs." (PMID 37370678, 2023). "In our study, the calibration curve reflected a high degree of agreement between the predictions of the model in the training and validation sets and the actual status, indicating that the model displayed good performance and reliability in predicting CDKN2A/B homozygous deletion in gliomas." (PMID 37190513, 2023). "The significance of CDKN2A/B alterations in gliomas is difficult to assess in historical cohorts." (PMID 37504251, 2023). "Consist with our studies, multiple studies have revealed that genomic alterations in CDKN2A was the most commonly phenomenon in cancers, including neck cancers (50%), pancreatic and esophageal cancers (47%), gliomas (35%), implying the correlation between CDKN2A alterations and tumors." (PMID 37653738, 2023). "Further analysis of the relationship between CRGs and the prognosis of gliomas revealed that high expression of FDX1, DLD, DLAT, and LIPT1 was associated with poorer survival in glioma patients, and high expression of CDKN2A and PDHA1 was significantly associated with better survival in gliomas." (PMID 36915038, 2023). "So, IHC might be proposed as a pertinent surrogate test to evaluate CDKN2A status when using our cutoff, and it will provide adequate prognostic data in each glioma subset." (PMID 36900302, 2023). "Therefore, loss of tumor-suppressor genes, notably CDKN2A/B, nullifies the tumor-suppressive activity of IDH mutation, resulting in progression to aggressive IDH-wildtype-like glioma." (PMID 35203456, 2022). "In sum, the prognostic importance of CDKN2A/B homozygous deletion in IDH-mutant glioma begs the question of how this genetic alteration impacts the biology of IDH mutation in relation to patient survival, and, importantly, how to develop a coherent strategy for the treatment of IDH-mutant glioma." (PMID 35203456, 2022). "Moreover, the homozygous deletion of CDKN2A/B, which was recognized as an indicator for more malignant biological behaviors in gliomas, was significantly more frequently observed in cluster 2, in line with the survival analysis." (PMID 36438805, 2022).